PTH (parathyroid hormone)
Diseases named in the same sentence as PTH in open-access papers (continued):
Sharing a sentence is not in itself a finding about the gene and the disease.
diabetes (continued). "This increased fracture risk in hemodialysis patients was associated with several factors, including time after KRT initiation, advanced age, comorbidities such as diabetes mellitus and liver cirrhosis, and metabolic disturbances like elevated PTH levels and chronic acidosis." (PMID 40899318, 2025). "While pulmonary and gastrointestinal disease remain the most common management challenges, CF also involves significant endocrine disease including diabetes, suboptimal fertility, and abnormal Ca homeostasis with perturbations of the parathyroid hormone (PTH)–vitamin D axis and bone mineral density." (PMID 41373955, 2025). "PD patients with diabetes had significantly lower levels of Ln_PTH in this study." (PMID 39791168, 2025). "Further, low serum Mg levels may result in an elevation of PTH, particularly in those with diabetes." (PMID 39791168, 2025). "Additionally, OP in the diabetes group was significantly influenced by menopause duration (B = 0.174, p = 0.009), age (B = 0.296, p = 0.007), albumin (B = 0.065, p = 0.034), and PTH (B = 0.029, p = 0.039)." (PMID 40428747, 2025). "Patients were stratified into APOA1 quartiles (0.29–1.05, 1.06–1.19, 1.20–1.34, and 1.35–2.49 ng/mL), and interquartile differences within lumbar BMD, β-CTX, age, BMI, triglycerides, ALT, UA, diabetes, hypertension, monocyte, hemoglobin, platelet, PTH, HDL, LDL, neutrophil and FAR." (PMID 39144661, 2024). "The patient characteristics, including age, sex, dialysis dose and vintage, prevalence of diabetes, arterial pressure, BMI, hemoglobin, electrolytes, and PTH levels, as well as medication used, were comparable between the light CONUT and moderate CONUT groups at three months post-COVID-19." (PMID 38804402, 2024). "This study gives an overview of the possible mechanisms involved in the association between calcium levels and inflammatory biomarkers, considering not only vitamin D and parathyroid hormone levels, but also other clinical conditions, such as diabetes mellitus and cardiovascular disease." (PMID 36350462, 2023). "Regarding medical variables, the low phosphorus group had a higher percentage of diabetes, lower diastolic pressure, lower concentrations of urea, creatinine, albumin, cCa, PTH, and CRP, and higher levels of glucose, triglycerides, and residual renal function (RRF)." (PMID 37497059, 2023). "On a subset of propensity-score matched patients, well balanced for sex, age, dialysis vintage, diabetes, albumin, hemoglobin, Calcium, Phospahte, PTH and therapies, PTX was confirmed to be a protective factor for overall survival (HR: 0.404 [0.254–0.643]; p = 0.00132)." (PMID 37351832, 2023). "In the present study, the low PTH group’s baseline characteristics were similar to those of the low PTH group in the previous study, namely older age and higher rate of diabetes compared with these variables in the SHPT group, and univariate analysis showed high mortality in the low PTH group." (PMID 35634511, 2022). "After adjusting for age, diabetes, high-sensitivity C-reactive protein, intact parathyroid hormone, LTM, and FM, multiple linear regression analysis revealed that serum leptin levels were significantly positively associated with REE in men rather than in women (P < 0.05)." (PMID 35369060, 2022). "It is confirmed that CKD patients with diabetes are more prone to present with low bone turnover states, the potential mechanisms probably lie in the suppression of parathyroid hormone secretion, osteoblast activity and bone turnover by hyperglycemia and insulin deficiency." (PMID 35459121, 2022). "Our results show consistency to be able to affirm that obese postmenopausal women have higher BMD values and lower than 25(OH)-vitamin D (associated with higher PTH levels) than non-obese women, without it seems that diabetes influences these parameters." (PMID 35789433, 2022).
diabetes (continued). "This study showed that there is an inverse correlation between the PhA and CAC score in patients on PD, even after adjusting for several variables such as age, sex, diabetes, glomerular filtration rate, BMI, hemoglobin, physical activity, calcium x phosphorus, PTH, and ultrasensitive CRP." (PMID 35990362, 2022). "In type 1 diabetes (T1DM) and T2DM sclerostin levels were found to be higher compared to non-diabetic controls which might be due to an impaired suppression of sclerostin production by PTH in patients with diabetes." (PMID 36190530, 2022). "Therefore, it seems that PTH and OC are independent factors protective against diabetes while promoting cholesterol abnormalities." (PMID 33833796, 2021). "Post-hoc analysis for pairwise comparison revealed that the IV group showed significantly lower diabetes comorbidity, serum adjusted calcium, magnesium, and bicarbonate, and higher serum alkaline phosphatase and intact PTH compared with the remaining two groups." (PMID 34787531, 2021). "However, our cross-sectional study design did not allow us to establish a temporal relationship between total 25(OH)D/PTH and development of these comorbidities or other diabetes-related cardiometabolic comorbid conditions." (PMID 34531372, 2021). "Serum 25OHD, Ca, and PTH levels should therefore not be regarded as independent risk factors for CAD in patients with diabetes." (PMID 34602077, 2021). "The following adjustments were performed in regression models: model 1, crude model; model 2: model 1 + age and sex; model 3, model 2 + BMI, serum albumin, and hemoglobin; model 4, model 3 + phosphorus, PTH, diabetes, hypertension, and cardiovascular disease; model 5, model 4 + eGFR and CRP." (PMID 34934591, 2021). "Jointly, compared to the group with 25(OH)D ≥50 nmol/L and PTH ≤6.89 pmol/L, white women with 25(OH)D deficiency (<50 nmol/L) had elevated risk for diabetes, regardless of PTH levels." (PMID 34531372, 2021). "White women with deficient 25(OH)D (<50 nmol/L) had higher risk of diabetes, regardless of their PTH level (HR = 1.46; 95% CI: 1.20–1.78 for those with normal PTH; HR = 2.30; 95% CI: 1.51–3.49 for those with excess PTH)." (PMID 34531372, 2021). "Serum 25OHD, Ca and PTH levels are more likely biomarkers rather than causal risk factors for CAD in patients with diabetes." (PMID 34602077, 2021). "Patients with PHPT have high concentrations of serum calcium or high concentrations of parathyroid hormone, or incorrect parathyroid hormone levels for serum calcium values, and represent the third most frequent endocrinopathy after diabetes mellitus and thyroid disease." (PMID 33472651, 2021). "Furthermore, comparing to women with higher OC and higher PTH levels, women with lower OC and lower PTH leves had higher risks of diabetes, hyperglyceridemia, and low HDL-C, while had lower risks of hypercholesterolemia and high LDL-C." (PMID 33833796, 2021). "Among a cohort of U.S. black and white postmenopausal women, deficient 25(OH)D levels (<50 nmol/L) were significantly associated with increased risk of diabetes in white women only, regardless of PTH levels." (PMID 34531372, 2021). "More interestingly, we also reported that PTH, independent of OC and 25(OH)D, was negatively associated with the prevalence of diabetes, hypertriglyceridemia, and low HDL-C." (PMID 33833796, 2021). "We were unable to examine whether there are any interactions between genetically predicted serum 25OHD, Ca and PTH levels and lifestyle/environmental factors on the risk of CAD in patients with diabetes." (PMID 34602077, 2021). "Although previous studies have showed that fractures are associated with several factors, such as duration of dialysis, diabetes mellitus, and PTH and ALP values, the present study showed that the GNRI is more strongly associated with fractures than these predictors." (PMID 34445007, 2021).
diabetes (continued). "The results showed that hypertension, diabetes, GERD, and fatty liver were significantly correlated with 25 (OH) D deficiency and MAU; Diabetes, hypercholesterolemia, hypertriglyceridemia are significantly associated with elevated PTH." (PMID 34322512, 2021). "Further classifying the population based on the median value of OC and PTH, low OC and low PTH subgroup had the highest OR, 95% CI for diabetes (1.873, 1.287–2.737) and the lowest OR, 95% CI for hypercholesterolemia (0.472, 0.324–0.688) and for high LDL-C (0.538, 0.376–0.771)." (PMID 33833796, 2021). "However, the body mass index, systolic/diastolic blood pressure, diabetes duration, direct bilirubin level, and serum PTH levels were distributed similarly among the four groups." (PMID 32781868, 2020). "Additionally, the interaction of hyperglycemia with the parathyroid hormone (PTH) and vitamin D system affects bone turnover in the population of patients living with diabetes mellitus." (PMID 31575077, 2019). "Our results suggest that PTH may have an inhibitory effect on the induction of sclerostin expression in alveolar bone by diabetes similar to results seen in a study of estrogen-deprived rats treated with PTH." (PMID 29544500, 2018). "Comparison of 25OHD, PTH and BMDs between different diabetes duration groups (x ̄±s)." (PMID 29190676, 2017). "The correlation between circulating PTH and bone markers may modulate bone turnover markers in diabetes patients with micro-vascular complications." (PMID 27826545, 2016). "Namely, patients in the PTX group were younger and had a lower prevalence of cardiovascular disease, diabetes, and malnutrition-inflammation syndrome, but with higher baseline serum PTH levels and DCC, as well as a more frequent use of alfacalcidol and cinacalcet." (PMID 27756251, 2016). "Compared with the quartile groups, the group with no PTH reduction included a higher proportion of African Americans and lower proportions of patients with diabetes as ESRD cause or comorbid condition." (PMID 25886282, 2015). "An experimental study using the diabetic Zucker (fa/fa) rat model with creation of femoral defects demonstrated that the administration of parathyroid hormone (PTH) could partially reverse the adverse skeletal effects of diabetes on bone defect." (PMID 25648962, 2015). "Our findings suggest that low serum Mg levels may cause insufficient parathyroid hormone action and may further lead to bone diseases in CKD patients with diabetes." (PMID 26273297, 2015). "In addition, linear regression analysis was performed to examine the impact of the serum Ca/Mg ratio on the PTH, also using sex, age, diabetes, and eGFR as adjusted variables." (PMID 26273297, 2015). "Predicting mortality in dialysis patients based on low intact parathyroid hormone levels is difficult, because aluminum intoxication, malnutrition, older age, race, diabetes, or peritoneal dialysis may influence these levels." (PMID 26107510, 2015). "The rate of progression of CKD may be affected by several factors, including age, gender, proteinuria, hypertension, diabetes mellitus and mineral-bone metabolism biomarkers (fibroblastic growth factor 23, serum phosphate and parathyroid hormone (PTH) levels)." (PMID 26016848, 2015). "The patients with diabetes presented lower levels of serum Ca, vitamin D, PTH, and serum Mg." (PMID 26273297, 2015). "Our findings suggest that low serum Mg levels may cause insufficient PTH action, and this may eventually cause lower turnover bone disease in CKD patients with diabetes." (PMID 26273297, 2015). "While insulins have long been a treatment mainstay for diabetes, the development of peptide drugs from somatostatin, calcitonin, parathyroid hormone (PTH), vasopressin, and glucagon like peptide-2 (GLP-2) classes have become important treatment options for metabolic indications." (PMID 24503632, 2014).
diabetes (continued). "With increasing PTH levels, age, BMI, serum levels of alkaline phosphatase, use of diuretics and urate-lowering agents, and the frequency of hypertension and diabetes tended to increase, whereas GFR, the proportion of whites, and serum levels of calcium, vitamin D, and phosphorus tended to decrease." (PMID 22405053, 2012). "Low 25(OH)D and high PTH concentrations were not independently associated with an increased risk of MetS, or diabetes." (PMID 23228198, 2012). "Elevated PTH levels may also impact cardiovascular health and the development of diabetes mellitus." (PMID 41048434, 2025). "Multiple regression analysis was adjusted sequentially for Mode 1 (gender, age, BMI, duration of diabetes, hypertension, smoking history, and drinking history), Mode 2 (Mode 1 and HbA1c, fasting C-peptide, fasting insulin, and eGFR), and Mode 3 (Mode 2 and Ca2+, Mg2+, PTH, and serum lipids)." (PMID 38904033, 2024). "As changes in parathyroid hormone levels related to 25(OH)D levels can have contradictory effects on muscle and bone function as well as glucose metabolism, a more in-depth investigation is needed to understand their effects on the complications of sarcopenia and diabetes." (PMID 38068813, 2023). "However, among T1D participants, we did not observe the expected suppression of PTH with increasing calcium intake (p = 0.370), and we observed a significant interaction of diabetes with calcium intake on the suppression of PTH (pinteraction = 0.022, β = 0.24)." (PMID 38025039, 2023). "Younger age, fewer male and diabetes mellitus patients, and less mortality compared to our patients might contribute to such discrepancy as the former three factors are also known PTH predictors, illustrating potential effect of other clinical and laboratory indicators." (PMID 35380083, 2022). "Overall, serum 25OHD, Ca, and PTH levels may not be causally associated with the risk of CAD in patients with diabetes." (PMID 34602077, 2021). "Serum 25OHD, Ca and PTH levels may not be causally associated with the risk of CAD in patients with diabetes." (PMID 34602077, 2021). "This could be due to the initial predominance of bone turnover inhibitoryconditions such as resistance to parathyroid hormone (PTH), reduced calcitriollevels, sex hormone deficiency, diabetes mellitus, and uremictoxins leading to suppression of various means of bone signaling." (PMID 29796575, 2018). "Finally, the function of the graft might be influenced by various factors, e.g. 33 % of patients with insufficient PTH secretion had diabetes mellitus of which 80 % revealed undetectable PTH levels (p <0.05)." (PMID 26467771, 2015). "However, relationship between serum Mg with PTH and bone mineral metabolism may vary with the presence of diabetes and different renal replacement therapies." (PMID 26273297, 2015). "Thirdly, the cross-sectional design may not conclude Mg deficiency as a cause of insufficient parathyroid hormone action in CKD patients with diabetes." (PMID 26273297, 2015). "Other significant variables include age (HR 1.072, P 0.0003), diabetes mellitus (HR 4.011, P 0.002), eGFR (HR 0.966, P 0.01), systolic blood pressure (HR 1.025, P 0.02), hemoglobin (HR 0.743, P 0.02), C-reactive protein (Ln) (HR 1.532, P 0.02) and PTH (Ln) (HR 1.680, P 0.01)." (PMID 24912660, 2014). "This low bone turnover in diabetes may be due to direct suppression of PTH secretion, since it has been shown in vitro that a high glucose concentration impairs the function of parathyroid cells and reduces secretion of PTH." (PMID 23843805, 2012). "Besides diabetes and age, only PTH and phosphate had significant direct effects on MS." (PMID 21306649, 2011). "Other variables related to Gensini scores included age, gender, smoking, diabetes, hypertension, eGFR, urinary albumin, phosphate, LDL-cholesterol, hemoglobin, hsCRP, and intact PTH." (PMID 41597410, 2026).
diabetes (continued). "Patients with diabetes have reduced levels of bone turnover markers, such as PINP, OCN, PTH, bone‐specific phosphatase, and CTX, and these bone metabolism markers have been reported to correlate with BMD and TBS." (PMID 41371233, 2025). "The significant inverse correlation between PTH and femoral neck BMD highlights a potential compensatory mechanism in bone metabolism in diabetes, an area that remains underexplored in the current literature." (PMID 40428747, 2025). "Subgroup analysis showed a significant relationship between PTH and the severity of WMH and PWMH in patients with diabetes (p for interaction < 0.05)." (PMID 41050279, 2025). "We observed significant differences in Age, Smoking status, Diabetes, Hypertension, AHM, ALT, TP, ALB, PAB, CR, cCa, PTH, and TG among the different groups." (PMID 38435391, 2024). "Factors such as low hemoglobin levels (Hb < 11 g/dl), elevated parathyroid hormone (PTH) levels, and a history of diabetes mellitus played a significant role in worsening cognitive function in these patients." (PMID 39408039, 2024). "The association between the IGF-1 index and low bone mass still existed (95% CI 0.02 (0.001–0.5), p=0.0209) even after adjusting for age, gender, CD duration, BMI, hypertension, dyslipidemia, diabetes, ALT, Scr, FT3, F24 pm, PTH, and osteocalcin." (PMID 37441368, 2023). "After adjusting for confounding factors, including age, the duration of diabetes, HbA1c, TC, TG, HDL, LDL, UA, Cr, and 24 h microalbuminuria (24 h-mAlb), GNRI was positively correlated with Ca, 25(OH)D, and PTH and negatively correlated with ALP and PINP." (PMID 36494810, 2022). "In correlation analysis, clinical indexes including serum phosphorus, PTH, Kt/V, CCr, nPCR, SGA scores, diabetes status, transport status (high average%) correlated well with BPV in different volume groups." (PMID 36415108, 2022). "The following variables have previously been reported as predictors of fracture risk in patients undergoing dialysis: older age, female sex, extremely high PTH values, long-term dialysis, higher values of bone-specific ALP, and diabetes mellitus." (PMID 34445007, 2021). "This association was evidenced by multiple stepwise regression analysis of variables that were independently associated with serum levels of CXCL16 including decreased eGFR, diabetes mellitus, hypertension, increased CRP and PTH levels." (PMID 33312065, 2020). "However, the regulation of PTH on sclerostin may be impaired in diabetes." (PMID 32851096, 2020). "The variables included in the MLR for the HGS outcome included age, excessive drinking, diabetes, hypercholesterolemia, menopause, vitamin C intake, and serum levels of HDL-c, LDL-c, and PTH." (PMID 32774854, 2020). "In the MLR for HGS/BMI, the following variables were included: age, excessive drinking episodes, diabetes, hypertension, hypercholesterolemia, menopause, and serum levels of HDL-c, LDL-c, TG, HbA1C, and PTH." (PMID 32774854, 2020). "In studies mainly on non-CKD population, sclerostin levels were correlated positively with age, male sex, diabetes, and bone mineral density (BMD) but inversely with physical activity and parathyroid hormone (PTH) levels." (PMID 31315601, 2019). "However, it remains to be determined whether the circulating levels of calcitonin, T4 and T3 and parathyroid hormone are reduced in MANF-deficient mice, which could, in addition to diabetes contribute to the retarded growth and reduced life-span in Manf−/− mice." (PMID 31781038, 2019). "Patients with lower serum 25(OH)D3 levels had a longer duration of diabetes, higher systolic blood pressure, HbA1c, LDL-C, PTH, carotid IMT, and plaque formation rate than those with higher 25(OH)D3 levels." (PMID 28459072, 2017). "Our result showed that PTH levels had positive correlation with OC as a bone formation and with CTX as a bone resorption in diabetes patients who suffering of DR/and or DN." (PMID 27826545, 2016).